INS (insulin)
Diseases named in the same sentence as INS in open-access papers (continued):
Sharing a sentence is not in itself a finding about the gene and the disease.
diabetes (continued). "Given the limitations in the access and license status of commercially developed automated insulin delivery (AID) systems, open-source AID systems are becoming increasingly popular among people with diabetes, including children and adolescents." (PMID 35834298, 2022). "It prevented the formation of diabetes characteristics by attenuating STZ-induced serum glucose elevation and serum insulin reduction." (PMID 35055468, 2022). "Diabetes mellitus (DM) is a comprehensive endocrine and metabolic disease characterized by glucose metabolism disorders, mainly resulting from insulin resistance or insufficient insulin secretion." (PMID 35211009, 2022). "Despite using diabetes technologies including continuous glucose monitoring (CGM), insulin pumps and contemporary insulin analogues, most women struggle to achieve and maintain the recommended pregnancy glucose targets." (PMID 35382796, 2022). "It has been discovered that in vivo deletion of miR-204 is protective against diabetes by increasing GLP-1R and insulin secretion." (PMID 36422510, 2022). "Many of them rely on the use of diabetes-related technologies, such as insulin pumps and continuous glucose monitoring (CGM), to manage diabetes on a daily basis." (PMID 36256804, 2022). "Due to either lack of insulin or pathogenic insulin reactive responses, diabetes can be divided into three groups: type 1 DM with low insulin production, type 2 DM with insulin resistance, and gestational diabetes with high blood sugar levels induced by diabetes recurrence during pregnancy." (PMID 35721855, 2022). "The MemAID was a 24-week trial of INI treatment with 24-weeks of follow-up, and this Safety sub-study in subcutaneous insulin treated T2DM has demonstrated the long-term safety and feasibility of this emerging treatment of diabetes complications in the brain." (PMID 35903156, 2022). "Mouse insulin promoter (MIP) and rat insulin promoter (RIP) are the most widely used promoters in diabetes and β cell regeneration research." (PMID 36700071, 2022). "Furthermore, a study conducted in India found that a provider-initiated patient-centered insulin-use health education program with information on sharps disposal significantly improved the knowledge and practice of used insulin sharps disposal among people with diabetes." (PMID 36568796, 2022). "Clinical studies in pre-diabetes and T2DM patients revealed a significant reduction in postprandial glucose levels, glucose iAUCs, and insulin levels following d-allulose supplementation." (PMID 35729673, 2022). "Type 2 diabetes mellitus (T2DM), the most prevalent type of diabetes mellitus (DM), is attributed to a progressive decrease in insulin secretion and insulin resistance." (PMID 35145929, 2022). "Intestinal barrier defenses and MyD88 are impaired in diabetes and ICAM and FMO3 expression induced while AhR ligands reverse diabetes-induced intestinal barrier damage, insulin insensitivity, FMO3/ICAM expression and systemic inflammation." (PMID 35966699, 2022). "In the course of Type 2 Diabetes Mellitus (T2DM), which accounts for nearly 90% of all cases of diabetes, the insulin response is inadequate, and this condition is defined as Insulin Resistance." (PMID 35454311, 2022). "In the progression of both type 1 diabetes mellitus (T1DM) and type 2 DM (T2DM), there comes a point where a threshold percentage of β-cells become dysfunctional, leading to a reliance on exogenous insulin administration for the treatment of patients with DM." (PMID 36139388, 2022). "We also matched the number and items of oral antidiabetic drugs, insulin use, and DCSI scores to balance the severity of diabetes mellitus in the study and control groups." (PMID 36298617, 2022). "Three additional patients who had pre-existing type II diabetes at baseline experienced worsening of their diabetes while on ICI and became insulin-dependent." (PMID 35350573, 2022).
diabetes (continued). "The current study aimed to reveal the correlation of beta-cell function and insulin sensitivity with glycemic control and weight control before and after medical nutrition therapy (MNT) in patients with newly-diagnosed type 2 diabetes mellitus." (PMID 35658859, 2022). "Type 2 diabetes mellitus (T2DM), one of the most prevalent types of metabolic disorders worldwide, mainly results from impaired insulin sensitivity and defective insulin secretory function by pancreatic beta cells." (PMID 35242882, 2022). "Furthermore, ASP stimulates insulin release from the pancreas, therefore the decrease in insulin level in CF may be associated not only with pancreatic damage, but also with a decrease in ASP levels in patients with CF-related diabetes." (PMID 36313742, 2022). "The following measurements were performed to identify prediabetes, diabetes and HOMA-IR: fasting glucose (FG), 2h postprandial glucose level (2h-PG), fasting insulin (FI), glycated hemoglobin HbA1c." (PMID 35204166, 2022). "In type 2 diabetes mellitus (T2DM), impaired pulsatile secretion of insulin has been demonstrated, suggesting a possible mechanism to explain the compromised insulin action in this pathology." (PMID 35741464, 2022). "Type-2 (non-insulin dependent diabetes mellitus (NIDDM)) diabetes is most common and occurs due to abnormal insulin secretion and its resistance." (PMID 35204283, 2022). "We have opted for repeated injections of small doses of STZ over high-fat diet or leptin receptor deficiency animal models of diabetes to enable cell lineage tracing and rule out any indirect effects, mediated by changes in insulin sensitivity or blood glucose, that may impact the islet plasticity." (PMID 34191257, 2022). "The frequency of females and overweight (BMI ≥25 and < 30 kg/m2) also increased, whereas eGFR levels and frequencies of prior diabetes mellitus, prior CVD, antihypertensive, insulin, and statin use decreased with higher TC levels." (PMID 36109725, 2022). "The mechanism of higher isoflavone intake was protective against MAFLD in the context of diabetes since isoflavones activated PPAR, which played a central role in the regulation of blood glucose homeostasis and insulin sensitivity." (PMID 36532560, 2022). "Type 2 diabetes mellitus (T2DM) is characterized by two major metabolic abnormalities: insulin resistance and insulin secretory dysfunction." (PMID 35672344, 2022). "Insulin use is widespread and necessary for advanced type 2 diabetes mellitus (T2DM) and type 1 diabetes mellitus (T1DM)." (PMID 35721710, 2022). "Type 2 Diabetes mellitus (T2DM), the most common type of diabetes, is characterized by inadequate beta-pancreatic cell (β-cell) function, insulin insensitivity and chronic inflammation, all of which progressively lead to impaired glucose homeostasis." (PMID 35207316, 2022). "Administration of CM (7 ml/kg for four weeks) compared with insulin therapy in experimental diabetes in rabbits, significantly reduced MDA serum levels compared to the insulin group." (PMID 35493477, 2022). "Specifically, it has been reported that anergy is lost in insulin-reactive B cells (IBCs), both in diabetes-prone NOD mice and people developing diabetes." (PMID 36275764, 2022). "Youths and young adults in the cohort spanned a broad age range at the same diabetes duration; thus, the study did not capture how the association between the insulin regimen and body fat may be different among youths diagnosed earlier in childhood versus later in childhood." (PMID 35127949, 2022). "Diabetes mellitus (DM) is a non-communicable disease characterizing chronic hyperglycemia caused by impaired functions in insulin secretion and/or insulin action." (PMID 36590224, 2022). "The prediction model is mainly composed of four predictors, namely duration of diabetes ≥ 10 years, BMI < 18.5 kg/m2, SDBG ≥ 3.0 mmol/L, and subcutaneous injection of insulin as the preoperative hypoglycemic regimen." (PMID 35538461, 2022).
diabetes (continued). "Therefore, a combination of a failure of exogenously delivered insulin to dissipate and widespread defects in other aspects of the hormonal and symptomatic counterregulatory response means that hypoglycaemia is both far more frequent and can be severe in type 1 (and longer‐duration type 2) diabetes." (PMID 36251572, 2022). "We show that there is a specific enrichment of TCR-β sequences known to respond to insulin and its precursor, preproinsulin (PPI), during the progression to clinical diabetes." (PMID 35998036, 2022). "As an example, phenolic acids exert an adjuvant effect on diabetes by activating the Phosphatidylinositol 3-kinase (PI3K)/Akt pathway, increasing the translocation of GLUT4 in adipose and muscle tissues and thus insulin sensitivity." (PMID 36235130, 2022). "Currently, the treatment of patients with diabetes and NAFLD includes the use of insulin sensitizing agents such as metformin and thiazolidinediones." (PMID 36072931, 2022). "Type 2 diabetes mellitus (T2DM) usually occurs in adults and is due to the pancreas being unable to produce fully functioning insulin in sufficient quantities." (PMID 35475576, 2022). "Insulin replacement therapy for 4 weeks in the STZ mice normalized the blood glucose and most of the diabetes-induced changes in the gene expression including Pepck, Pgc-1α, and Cyp3a11, among others." (PMID 35524739, 2022). "The patient was initially misdiagnosed as having fresh type 2 diabetes mellitus after the first episode of DKA, which was resolved by short-term insulin therapy and treated with oral anti-diabetic agents after the DKA was resolved." (PMID 36423001, 2022). "One problem that some surrogate markers have, more specifically fasting insulin, HOMA-IR, and AUC OGTT, is that they can be unreliable in certain populations such as the elderly and those with uncontrolled diabetes." (PMID 35631177, 2022). "Type 2 diabetes mellitus (T2DM) is the most prevalent form, affecting ~90–95% of diabetic subjects, and is characterized by decreased β-cell insulin secretion and/or insulin resistance, resulting in chronic hyperglycemia (elevated blood glucose levels)." (PMID 36076823, 2022). "A knockdown of GSK-3α in mice showed increased sensitivity towards insulin, suggesting the significant role of GSK-3α in glucose synthesis and as a therapeutic target for diabetes." (PMID 36497091, 2022). "Additionally, the therapies administered to diabetic patients, including sulfonylureas, metformin, thiazolidinediones, and insulin, as well as the effects of diabetes on the immune system, may potentially affect the host’s response to sepsis and clinical endpoints." (PMID 36699043, 2022). "Insulin signalling upstream of p38; restores ATF6-related autophagy; insulin resistance, diabetes and Alzheimer’s pathophysiology." (PMID 35037854, 2022). "The blood glucose and insulin AUC of the mice treated with COS decreased faster (p < 0.05) than in the diabetes model group, suggesting that COS increased the utilization efficiency of insulin and improved insulin sensitivity." (PMID 38647883, 2022). "Our findings provide mechanistic insights into regulation of insulin sensitivity during physiological ageing and highlight MT1-MMP as a promising target for therapeutic avenue against diabetes." (PMID 35768470, 2022). "T1DM occurs primarily due to autoimmune destruction of insulin-producing β cells in the islets of the pancreas, which accounts for 5–10% of cases, while T2DM accounts for ~ 90% of all cases of diabetes." (PMID 35499716, 2022). "One of the main problems associated with the lack of a permanent ‘cure’ for diabetes versus long term treatment as a way of managing the disease, is the fact that once damaged, beta cells have a limited ability to proliferate and expand to restore insulin production." (PMID 34542797, 2022). "Type 2 diabetes mellitus (T2DM) is the most prevalent and occurs due to the insufficient production of insulin by the body, insulin resistance, and obesity." (PMID 36013325, 2022).
diabetes (continued). "Several studies have demonstrated the beneficial effects of MC against diabetes by regulating GLP-1, which is crucial in stimulating insulin gene transcription." (PMID 36009342, 2022). "Among men, they found that insulin levels, obesity and cholesterol were the main determinants, and higher quartiles of AIP significantly predicted coronary heart disease, diabetes and hypertension." (PMID 35409811, 2022). "We showed that following the induction of diabetes, the area under the glycemic curve of ITT compared to the NDC group, increased while the response of insulin target cells to exogenous insulin decreased." (PMID 35725834, 2022). "Numerous studies have shown that the STZ and NA diabetes model is valuable in investigations of various aspects of diabetes since STZ is known to damage pancreatic B-cells, while NA is given to rats to partially protect insulin-secreting cells against STZ." (PMID 36362316, 2022). "Other experiments showed that overexpression of ANGPTL8 in db/db mice and mice with diabetes induced by high-fat diet/streptozotocin, reduces FBG levels and enhances glucose tolerance and insulin sensitivity, while ANGPTL8 knockdown has the opposite effect." (PMID 36295827, 2022). "In the present study, we investigated whether the MDS and/or the DII® score was associated with measures of body composition, insulin resistance and secretion, blood pressure, lipids, cytokines and adipokines in individuals who were either overweight or obese without diabetes." (PMID 36297122, 2022). "The inhibition of lncRNA-H19 resulted in impairment of the insulin–phosphatidylinositol 3-kinase (PI3K)–Akt pathway, resulting in impaired angiogenesis and wound healing in diabetes." (PMID 36297381, 2022). "Second, the prolonged activation of estrogen receptor ERα by the environmental estrogen could lead to excess insulin release, pancreatic β-cell exhaustion, and peripheral insulin resistance, which may result in glucose metabolism disorder and contribute to the development of diabetes." (PMID 35578291, 2022). "Previously, we demonstrated that knockout mice for peroxiredoxin 6 (Prdx6-/-), an antioxidant enzyme with both peroxidase and phospholipase A2 activity, develop a mild form of diabetes mellitus with a reduction in GSIS and in peripheral insulin sensitivity." (PMID 35370943, 2022). "In this work, we demonstrate the potential protective effects of adipose-derived cell treatment in modulating diabetes-induced DPP4 activity, insulin resistance, and systemic inflammation." (PMID 35883204, 2022). "The main pathophysiology of type 2 diabetes mellitus (T2DM) is decreased insulin sensitivity and decreased insulin secretion ability." (PMID 35115614, 2022). "The most common forms of diabetes are type 1 diabetes, where complete insulin deficiency leads to autoimmune destruction of the pancreatic islet beta cells (insulin-dependent diabetes), and type 2 diabetes, where cells do not respond normally to insulin (insulin resistance)." (PMID 36011665, 2022). "Neuronal exosomes taken from blood samples from patients that took part in this clinical trial showed improvements in insulin signaling in the brain, similar to GLP-1 drug effects in diabetes." (PMID 36117625, 2022). "Type 2 diabetes mellitus (T2DM) is a chronic condition that develops when the body cannot effectively produce and utilize insulin." (PMID 36494651, 2022). "Therefore, findings in this non-diabetic population, especially both higher post load 2h glucose and higher insulin response were significantly associated with the increased risk of all-cause death and CVD death, may also have some implications for people with diabetes." (PMID 35090539, 2022). "Numerous studies have shown that MC counteracts diabetes by controlling GLP-1, which is essential for promoting insulin gene transcription." (PMID 36009342, 2022).
diabetes (continued). "The mean ± SD of disease duration of diabetes for T2DM group was 6.98 ± 7.97 years and there were 465 patients taking insulin and 1,436 patients taking glucose-lowering medications in all 2,476 patients with T2DM patients." (PMID 35495951, 2022). "Additionally, RAPID provides insulin‐mediated blood‐glucose control by a single oral dose of a clinically licensed drug, which advances the treatment options for diabetes, may improve patient convenience, and could make regular daily insulin injections a thing of the past." (PMID 35048556, 2022). "As well as stimulating glucose‐dependent insulin secretion, GLP‐1 exerts additional effects of pancreatic beta‐cells with obvious therapeutic benefits in diabetes." (PMID 33822370, 2022). "Other approaches focusing on liquid biopsy biomarkers for the management of diabetes have examined methylation of INS, IAPP and GCK either as single parameters or as combined parameters, i.e., INS and CHTOP in a duplex assay." (PMID 35207316, 2022). "Regardless of the type of diabetes, the primary pathogenesis of this chronic disease is blood glucose dysregulation which results in hyperglycemia, and is associated with insulin resistance or a lack of insulin secretion due to pancreatic β-cell dysfunction or cell death." (PMID 36213227, 2022). "In addition, in several studies Silibinin has been shown to be an insulin sensitizer and could effectively reduce glucose plasma concentrations in type 2 diabetes mellitus and NAFLD patients, reflected in an enhanced homeostasis model assessment of insulin-resistance values." (PMID 35999630, 2022). "The newly identified mtDNA encoded polypeptide MOTS-c improves insulin sensitivity, regulates glycolipid metabolism, and affects mitochondrial metabolism, leading to suggestions that MOTS-c could be a new treatment for diabetes, and for reducing myocardial damage in diabetes." (PMID 36687680, 2022). "In diabetes, LSD1 inhibition enhanced insulin secretion in response to glucose stimulation in insulin-producing cells." (PMID 34983623, 2022). "Type 2 diabetes mellitus (T2DM) is one of the metabolic diseases resulting from defective insulin secretion and/or insulin action, and it makes up about 90% of all cases." (PMID 36014875, 2022). "Insulin, the oldest U.S. Food and Drug Administration(FDA)-approvedrecombinant protein and a World Health Organization (WHO) essentialmedicine for treating diabetes globally, faces challenges due to itsstorage instability." (PMID 35968684, 2022). "In this “real world” study, glycaemic control has been investigated in the context of RF in children and adolescents with type 1 diabetes mellitus (T1DM) and compared multiple daily injections (MDI) and continuous subcutaneous insulin infusion (CSII) outcomes." (PMID 35399686, 2022). "However, reduced insulin secretion due to under nutrition could also contribute to diabetes." (PMID 35992098, 2022). "Urolithin A alleviates diabetes and pancreatic damage by activating the AKT/mTOR pathway to regulate insulin signaling and autophagy to reduce oxidation, inflammation and apoptosis in the pancreas of type 2 diabetic mice." (PMID 36235858, 2022). "Insulin is a lifesaving medicine and is an absolute requirement for patients with type 1 diabetes mellitus (T1DM) and an increasing need for type 2 diabetes mellitus (T2DM) patients." (PMID 35431962, 2022). "Appropriate estimations of insulin sensitivity factor (ISF) and insulin-to-carbohydrate ratio (ICR) in children and adolescents with type 1 diabetes mellitus (T1DM) using intensive insulin therapy are essential for proper calculation of bolus insulin doses." (PMID 35350271, 2022). "This evidence indicates that there is a relationship between insulin/glucose and LH/FSH levels in serum and that their ratio is affected in diabetes." (PMID 36144807, 2022). "As type 2 diabetes mellitus (T2DM) progresses, β-cell dysfunction and failure require insulin to achieve optimal glycaemic control." (PMID 36224294, 2022).